MTOR (mechanistic target of rapamycin kinase)
Diseases named in the same sentence as MTOR in open-access papers (continued):
Sharing a sentence is not in itself a finding about the gene and the disease.
tumor (continued). "Comparing primary tumor and brain metastases samples from the same patient, we observed increased mTORC1 activity in metastases; in 60% of the cases, p-mTOR and p-S6 expression was increased in brain metastases, whereas in 40% of cases, Rictor expression was increased in brain metastases." (PMID 38515456, 2024). "Notably, the mTOR-mediated signaling pathway, especially mTORC1 signaling, has the ability to facilitate tumor cell survival, migration and metastasis through the P70 S6K-mediated pathway as well as the 4EBP1-mediated pathway." (PMID 39048994, 2024). "Gene set variation analysis (GSVA) revealed that signaling pathways associated with tumor progression, including PI3K/Akt/mTOR signaling, Notch signaling, angiogenesis signaling, and epithelial–mesenchymal transition (EMT), were significantly enriched in malignant cells with high PRKAA2 expression." (PMID 38424484, 2024). "Also, a feedback loop between TAM-released CCL2 and activated PI3K/Akt/mTOR pathway in tumor cells is a possible mechanism for endocrine resistance in breast cancer patients." (PMID 39003350, 2024). "miR-21 expression is associated with tumor growth and metastasis, by suppressing tropomyosin alpha-1 (TPM1) and programmed cell death 4 (PDCD4), affecting the mammalian target of rapamycin (mTOR) pathway." (PMID 39335585, 2024). "Some studies have demonstrated that the use of everolimus, a selective mTOR inhibitor, in combination with ribociclib (a kinase inhibitor) or bortezomib (a proteosome inhibitor), can enhance inhibition of tumor growth and lead to stable disease, increasing overall survival." (PMID 39769278, 2024). "The mTOR signaling pathway is related to tumor cell survival." (PMID 38473249, 2024). "Similarly, samples in cluster C2 displayed higher expression in multiple tumor-associated physiological pathways including AKT, EGF, HER2, MAPK, MET, mTOR, PTEN, RAS, WNT and NOTCH signal pathway." (PMID 38434969, 2024). "Hence, mTOR is constantly activated in tumors to keep tumor cells proliferating and surviving and it serves a crucial function in tumor cell biology." (PMID 38965615, 2024). "Hyperactivation of the mTOR pathway contributes to tumor initiation and progression." (PMID 38671459, 2024). "Furthermore, several studies have suggested the involvement of mTOR signaling in chemokine-mediated immune cell chemotaxis during tumor progression." (PMID 38791040, 2024). "In addition, osteopontin can also promote tumor growth and metastasis in TNBC, by activating the PI3K/AKT/mTOR pathway, elevating BC cell proliferation, invasion, and migratory abilities, tumor sphere formation, and angiogenesis." (PMID 39456858, 2024). "Also, authors suggested that miR-99b-5p is collaborated with more prolonged overall survival of patients and acts as a tumor suppressor in metastatic CRC by targeting mTOR." (PMID 38632250, 2024). "Above all, it is reasonable to speculate that SGs formation may be the main reason for tumor cell insensitivity to the dual PI3K/mTOR inhibitor." (PMID 38238825, 2024). "The PI3K/AKT/mTOR signal to downstream proteins leads to the development of tumor resistance." (PMID 38334632, 2024). "Additionally, mTOR inhibitors improve the tumor microenvironment by increasing immune cell infiltration, further enhancing antitumor immune responses." (PMID 39840028, 2024). "In a xenograft model, combined BET degradation and mTOR inhibition induced tumor regression." (PMID 38060314, 2024). "Previous studies have demonstrated that the mTOR signaling pathway is crucial in tumor progression." (PMID 39593172, 2024). "Furthermore, the mTOR expression significantly decreased in tumor tissues compared to controls (U= 23.06, p<0.001)." (PMID 38164366, 2024).
tumor (continued). "Similarly, we have recently shown that mTOR inhibition with everolimus in the adjuvant setting after definitive treatment of locally advanced HNSCC lesions reduces significantly tumor relapse, specifically in HPV− cases." (PMID 38954773, 2024). "The PI3K/AKT/mTOR (mammalian target of rapamycin) signalling pathway regulates cell growth, survival, motility, metabolism, and angiogenesis, and its activation contributes to tumor development and resistance to anticancer therapy." (PMID 38797813, 2024). "In addition to the cellular response to hypoxia, TPX2 positively correlated with multiple carcinogenesis-related pathways, such as the PI3K/AKT/mTOR pathway, tumor proliferation signature, and MYC targets." (PMID 38833082, 2024). "As such, their conclusion advised that K17’s oncogenic role in OSCC tumor growth may not only be through the Akt/mTOR pathway but also the suppression of apoptosis." (PMID 38891785, 2024). "The results revealed that the PI3K/AKT/mTOR pathway was the most active in UPP1high tumor cells." (PMID 38331898, 2024). "Additionally, in vivo experiments using a subcutaneous tumor model in mice, established with the mEC25 cell line, demonstrated that MTOR knockdown slowed tumor growth and prolonged survival." (PMID 39742278, 2024). "By analyzing the impact of prolonged curcumin supplementation on tumor incidence, growth, and molecular signaling pathways (NF-κB, mTOR, p70S6K1, 4E-BP1, Nrf2/HO1), this research aims to uncover curcumin’s mechanisms of action and assess its viability as a dietary intervention for LM prevention." (PMID 39770574, 2024). "Also, we tested the expression of EGFR, ErbB2, p-AKT, and p-mTOR in 4 groups of tumor tissues through western blot." (PMID 39075515, 2024). "In addition, we used LY-294002 (AKT inhibitor) and Rapamycin (mTOR inhibitor) to evaluate the effects of inhibitors alone or in combination with overexpression of PDHK1-241aa on the tumor biological behavior of ccRCC cells." (PMID 38360682, 2024). "They further illustrated that the anti-tumor effect of NRBP2 may be mediated by the AMPK/mTOR pathway." (PMID 38778371, 2024). "Moreover, one of the central checkpoints of negatively regulated autophagy is mTOR, and inhibition of PI3K-AKT-mTOR signaling significantly stimulate autophagy and restrain tumor growth." (PMID 38791141, 2024). "GSEA pathway enrichment displayed an upregulation of interferon and inflammatory pathways in responders, while a number of tumour-promoting signalling pathways were downregulated including G2M checkpoint, mTOR, hedgehog, TGF-beta, WNT signalling and epithelial-mesenchymal transition." (PMID 38227740, 2024). "Despite these findings, whether LINC01605 regulates tumor cells via the mTOR signaling pathway remains unclear." (PMID 39048994, 2024). "Therefore, the regulation of mTOR signaling due to PUFA metabolites appears as one of the key mechanisms due to mTOR-mediated inflammation affecting the tumor microenvironment." (PMID 39290706, 2024). "The results of the KEGG analysis showed that the PI3K/AKT pathway was significantly up-regulated, which was in line with existing studies that emphasize the importance of the PI3K/AKT/mTOR pathway in regulating the growth, survival and metabolism of various tumor cells." (PMID 38993570, 2024). "Inhibition of PI3K in vitro resulted in decreased proliferation and increased cell death in primary CD4+ PTCL cells harvested from patient lymph nodes, further illustrating the reliance of canine CD4+ PTCL on PI3K/AKT/mTOR signaling for tumor cell proliferation and survival." (PMID 38166662, 2024). "Now, there is a dynamic balance between stress granules and mTOR in the tumor cell." (PMID 38238825, 2024). "Furthermore, the G-CSF group exhibited a notable reduction in SHP-2 expression, alongside a substantial elevation in the phosphorylation levels of the PI3K/AKT/mTOR pathway proteins across all tumor-bearing paradigms." (PMID 38967628, 2024).
tumor (continued). "The PI3K/Akt/mTOR pathway exerts a profound influence on a myriad of biological processes, playing a pivotal role in the regulation of cell survival, growth, proliferation, and tumor angiogenesis." (PMID 38844562, 2024). "In addition, GAS5 is downregulated during CRC progression and functions as a competitive endogenous RNA for miR-34a,which is involved in the regulation of GAS5-inhibited tumor cell autophagy and triggers apoptosis via the mTOR/SIRT1 pathway." (PMID 39830506, 2024). "Our findings suggest the upregulation of PD-L1 may be related with activation of the mTOR pathway in the early events of tumor progression and the pathogenesis of OSCC." (PMID 38370876, 2024). "CD109 may amplify this process, as it interacts with EGFR to activate the Akt/mTOR pathway, driving tumor growth." (PMID 39990858, 2024). "Notably, OPN can induce proliferation, invasion, migration and angiogenesis in tumor cells by activating the PI3K/AKT/mTOR pathway." (PMID 38526702, 2024). "Similarly, the PTEN/AKT/mTOR pathway has been reported to be closely related to cell proliferation and chemoresistance in a variety of tumours." (PMID 39114365, 2024). "The mTOR signaling pathway promotes tumor cell survival, proliferation, and cell cycle progression." (PMID 39555093, 2024). "Additionally, in tumours subjected to PI3K/mTOR inhibitors, alone or in combination with anti‐PD‐1 therapy, we observed the repolarisation of macrophages towards an anti‐tumourigenic (M1‐like) phenotype." (PMID 38711203, 2024). "In addition to MMPs, c-Jun N-terminal kinase/stress-activated protein kinase (JNK/SAPK) and mammalian target of rapamycin (mTOR) are related to elevated tumor growth, proliferation, survival, invasion, and metastasis." (PMID 39086858, 2024). "Adding ccGAS as a biomarker may help optimize strategies combining mTOR inhibitors with KGA blockade to eliminate persistent quiescent chemoresistance tumours." (PMID 39080411, 2024). "The network pharmacology and molecular docking analyses predicted that HCS inhibits the growth of and progression of BRCA by inactivating the PI3K-Akt/mTOR signaling pathway, which is known to regulate the proliferation, apoptosis, and migration of tumor cells." (PMID 38753638, 2024). "To elucidate the potential regulatory role of B7-H3 in modulating HIF-1α expression through the PI3K/Akt/mTOR signaling pathway and its impact on downstream glycolysis-related proteins, we conducted immunofluorescence staining on tumor tissues collected from xenograft mouse models." (PMID 38577598, 2024). "Moreover, STAT3 signaling was inhibited when various tumor cell lines were received treatment of mTOR inhibitor rapamycin, which supports our observation that STAT3 phosphorylation was inhibited by the combination of PQR309 and gemcitabine." (PMID 38555280, 2024). "Additionally, PD-L1 promotes the expression of glycolytic enzymes by facilitating the Akt/mTOR signaling pathway in tumor cells within the tumor microenvironment, leading to the translation of Glut1, further intensifying tumor glycolysis." (PMID 39596288, 2024). "Whether the response to other ROS inducing and DNA damaging therapeutic interventions, i.e., irradiation, is modulated by mTOR inhibition in a similar manner needs further investigation and might differ between different tissues and tumor entities." (PMID 38182566, 2024). "The increased expression of hypoxia-inducible factor-1-α leads to the overexpression of the PI3K/AKT/mTOR pathway, as well as glucose transporters such as glucose transporter 1, leading to increased glucose consumption and acidification of the tumor microenvironment." (PMID 38410760, 2024). "V-ATPases regulate intracellular tumor signaling pathways such as Wnt, Notch, and mTOR." (PMID 38486234, 2024).
tumor (continued). "Therefore, further investigations of targeted mTOR inhibition will allow one to study the transition of tumor cells to selective translation of mRNAs and explore the activation of TFEB-dependent autophagy and lysosomes with a focus on lysosomes." (PMID 38418814, 2024). "Additionally, alterations in the expression of key proteins associated with the PI3K/AKT/mTOR and EMT pathways, including p-PI3K, p-AKT, p-mTOR, E-cadherin, N-cadherin, and Slug, further substantiate the regulatory role of HSPB6 in modulating tumor dynamics." (PMID 39608715, 2024). "Also, downstream mTOR is a vital protein kinase of this pathway able to regulate the biological effects of tumor cell growth, proliferative ability, survival as well as angiogenesis." (PMID 38526702, 2024). "Therefore, p62 protein expression in tumor tissue was compared with the ΔCt value of Beclin1 or mTOR gene expression in tumor tissues." (PMID 38164366, 2024). "The deep response of TSC tumor indicated a strong sensitivity for everolimus, which may suggest a dominant role of mTOR pathway in TSC tumor development." (PMID 39279295, 2024). "Interestingly, the three patients treated with a lead-in of alisertib who had a persistent decrease in caspase in tumor tissues despite the addition of mTOR pathway activation experienced disease progression as best response to treatment." (PMID 38672538, 2024). "Ridaforolimus demonstrated its ability to cross the blood–brain barrier and inhibit mTOR activity, as evidenced by a decrease in its downstream effectors in tumor specimens; pS6 levels were reduced, and phosphorylated 4E-BP1(p4E-BP1) was reduced by >80% compared to patient serum baseline." (PMID 38474373, 2024). "HEL also targets the mTOR/p70S6K pathway, further contributing to its anti-tumor effects." (PMID 39906672, 2024). "This autosomal dominant genetic predisposition with high penetrance arises from heterozygous germline variants in the PTEN tumour suppressor gene, leading to dysregulation of the PI3K/AKT/mTOR signalling pathway, which promotes the overgrowth of multiple and heterogenous tissue types." (PMID 38792950, 2024). "Dual-luciferase assays verified that miR-485-3p may want to directly bind to Akt3 mRNA, inhibiting the Akt/mTOR pathway in tumor cells, thus inhibiting cellular glycolysis, proliferation, and invasion, and acting as a tumor suppressor." (PMID 39119480, 2024). "Loss-of-function mutations in one of two tumor suppressor genes, TSC1 and TSC2, lead to the overactivation of the mechanistic target of rapamycin (mTOR) pathway, dysregulation of cell proliferation, and the formation of benign tumors in multiple organ systems, including the brain." (PMID 38812055, 2024). "The mTOR pathway, critical in cell growth and survival, has also been identified as a therapeutic target, with inhibitors like rapamycin and everolimus reducing cell metabolism, Glut1 and HIF1α expression, and overall tumor progression." (PMID 39590345, 2024). "NF2 may regulate PD‐L1 expression through the PI3K–AKT–mTOR pathway, anti‐PD‐L1 antibody may have a synergetic effect with the mTOR inhibitor in reducing tumor cell proliferation." (PMID 38828669, 2024). "Overexpression and activation of receptor tyrosine kinases (RTKs), genetic alterations in the phosphatidylinositol 3-kinase (PI3K) pathway components, a hypoxic tumor microenvironment, and chronic inflammation collectively contribute to Akt-mTOR pathway hyperactivation." (PMID 38890304, 2024). "In addition, the PD-1/PD-L1 axis regulates the PI3K/Akt/mTOR pathway, which is involved in the immunosuppressive tumour microenvironment." (PMID 39075562, 2024). "In addition, we suggested a functional role for the PI3K-Akt-mTOR pathway in these neoplasms with potential clinical relevance." (PMID 38191367, 2024). "The duration of mTOR suppression-based quiescence may determine the phenotypic outcomes in tumor cells after resumption to proliferation." (PMID 38418814, 2024).
tumor (continued). "Moreover, the proteomic analysis of SN-MM cell lines revealed that RICTOR, a subunit of mTORC2 complex, is the most significantly activated upstream regulator, suggesting a relevant role for the PI3K-Akt-mTOR pathway in these neoplasms." (PMID 38191367, 2024). "EGFR and PTEN could alter receptor tyrosine kinase (RTK)/PI3K/AKT/mTOR pathway and promote tumor progression." (PMID 39208202, 2024). "Combining the results of LC–MS/MS and GO analysis, PEC controlled the expression of 582 proteins in the AGS-xenografted tumor, and it was shown to be implicated in pathways such as PI3K/AKT/mTOR, HIF-1, and Wnt, as well as the cell cycle, apoptosis, and ferroptosis." (PMID 38361124, 2024). "Overall, the activation of the PI3K/AKT/mTOR pathway in MM cells, coupled with interactions within the bone marrow microenvironment, leads to enhanced cell proliferation, migration, and survival, ultimately promoting tumor growth and dissemination." (PMID 38961036, 2024). "Additionally, BEZ235 (Dactolisib), a dual PI3K/mTOR inhibitor, has shown antitumor activity in preclinical models of HCC by targeting the PI3K/AKT/mTOR pathway, reducing tumor cell proliferation and inducing apoptosis." (PMID 39156976, 2024). "Beyond tumor reduction, emerging data suggest that mTOR inhibitors may also ameliorate certain neuropsychiatric manifestations of TSC." (PMID 39727664, 2024). "In an attempt to anticipate the response to mTOR inhibitors, an intriguing study found that the degree of phosphorylated S6 ribosomal protein expression, which indicates mTOR pathway activation, was predictive of early tumor response to the treatment." (PMID 39026968, 2024). "In addition, phosphatase and tensin homolog deleted on chromosome ten (PTEN) is a typical tumor suppressor gene that inhibits the PI3K/Akt/mTOR growth signaling cascade." (PMID 38166086, 2024). "This evolutionary theory could explain the molecular mechanisms that emerged during tumor evolution in the patient in our case after mTOR inhibitor treatment, and restoration of these alterations would re-sensitize cells in HER2-low MBC to MTAs." (PMID 38344201, 2024). "And the inhibition of IGF-1R itself or the downstream signal transduction cascade, namely, the PI3K/AKT/MTOR pathway, exerts potent stimulation on autophagy and other adaptive mechanisms to achieve anti-tumor efficacy." (PMID 38665430, 2024). "Salmonella treatment targets β3-adrenoceptor and AKT/mTOR pathways in tumor growth and progression." (PMID 38356700, 2024). "However, while FDFT1 acts as a tumor suppressor by negatively regulating AKT/mTOR/HIF1α signaling in CRC cells, SQLE activates the β‐catenin oncogenic pathway." (PMID 38517197, 2024). "Similarly, miR-210 promotes HCC progression by enhancing autophagy in M2-polarized macrophages through inhibition of the PI3K/AKT/mTOR signaling pathway, thereby fostering tumor cell proliferation, invasion, and immune evasion in the tumor microenvironment." (PMID 39876897, 2024). "Upregulation and activation of MOR may promote tumor proliferation via the PI3K/Akt/mTOR pathway and blockage of MOR may sensitize HNSCC to chemotherapy." (PMID 36835812, 2023). "Altogether, these data illustrate the pro-tumoral effect of intracellular S100A9 in AML, regulating mTOR-ER stress signaling pathways which may contribute to tumor progression and drug resistance." (PMID 38110349, 2023). "Therefore, various studies showing inhibition of mTOR leading to induction of autophagy using various drugs emphasize the paradoxical effect of autophagy on tumor progression." (PMID 36760166, 2023). "Furthermore, the reduced level of HIF reduces the expression of the GLUT-1 transporter and consequently decreases glucose uptake into tumour cells, lactate production, Akt and mTOR signalling, and cell viability, depending on the dose and time." (PMID 37446252, 2023).